PFKFB4 (6-phosphofructo-2-kinase/fructose-2,6-biphosphatase 4)
Description:
Synthesis and degradation of fructose 2,6-bisphosphate.
Tractability: Small molecule: a high-quality ligand is known. PROTAC: ubiquitination databases record sites on it; its protein half-life has been measured; a small molecule that binds it is known.
Target class: Enzyme
Gene: Protein-coding gene on chromosome 3 (48,517,684 to 48,562,015, reverse strand). Ensembl gene ENSG00000114268.
Subcellular location (Human Protein Atlas): Nucleoli
Pathways (Reactome):
Metabolism: Regulation of glycolysis by fructose 2,6-bisphosphate metabolism
Gene Ontology:
Molecular function: 6-phosphofructo-2-kinase activity; protein binding; ATP binding; catalytic activity; fructose-2,6-bisphosphate 2-phosphatase activity
Biological process: gluconeogenesis; glycolytic process; positive regulation of glycolytic process; fructose 2,6-bisphosphate metabolic process; fructose metabolic process
Cellular component: cytosol
Genetic constraint (gnomAD): Loss-of-function variants: 36 observed, 51.96 expected, observed/expected ratio (o/e) 0.69, 90% interval 0.53 to 0.92. The upper end of that interval is the gene's LOEUF score, 0.92, which puts it in group 3 of 6, group 1 being the genes least tolerant of losing a copy. Missense variants: 410 observed, 565.96 expected, observed/expected ratio (o/e) 0.72, 90% interval 0.67 to 0.79. Synonymous variants: 180 observed, 218.45 expected, observed/expected ratio (o/e) 0.82, 90% interval 0.73 to 0.93.
Homologues: Orthologues: chimpanzee PFKFB4 (100% identical), macaque PFKFB4 (99% identical), rabbit PFKFB4 (99% identical), dog PFKFB4 (99% identical), guinea pig PFKFB4 (99% identical), mouse Pfkfb4 (97% identical), pig PFKFB4 (94% identical), rat Pfkfb4 (92% identical), tropical clawed frog pfkfb4 (83% identical), zebrafish pfkfb4b (83% identical), zebrafish pfkfb4a (81% identical), Drosophila melanogaster Pfrx (57% identical), and 2 more. Paralogues in human: PFKFB1 (75% identical), PFKFB3 (69% identical), PFKFB2 (67% identical).
Diseases named in the same sentence as PFKFB4 in open-access papers:
PFKFB4 is named in the same sentence as 65 diseases in open-access papers, as found by Europe PMC text mining. Sharing a sentence is not in itself a finding about the gene and the disease. The quoted sentences say what the papers report.
breast cancer (37 papers, 2018 to 2025). A primary or metastatic malignant neoplasm involving the breast. "It is reported that PFKFB4-mediated glycolysis pathway is associated with stemness features of breast cancer." (PMID 37919747, 2023). "Our previous research found that the PFKFB4K173A mutation plays a key role in PFKFB4-mediated glycolysis and maintenance of breast cancer stemness." (PMID 34976184, 2022). "The upregulation of PFKFB4 was reported in multiple cancer types and was associated with the aggressiveness of tumors such as in bladder cancer, breast cancer, lung cancer, and ovarian cancer." (PMID 31847435, 2019). "In this study, we evaluated the relationship of the cancer metabolic enzyme PFKFB4 with the risk of recurrence, metastasis and death in operable breast cancer." (PMID 31244553, 2019). "High expression of PFKFB4 was associated with poor prognosis of operable breast cancer." (PMID 33593309, 2021). "PFKFB4-mediated glycolysis was associated with cancer stemness in breast cancer, while the inhibition of this protein may lead to improved outcome for patients." (PMID 34593007, 2021). "The overexpression of PFKFB4 was found to be associated with a poor prognosis in gastric cancer, bladder cancer, colon cancer, acute monocytic leukaemia, glioblastoma, thyroid cancer, and breast cancers." (PMID 33407546, 2021). "In breast cancer, hypoxia-induced PFKFB4 in the tumor microenvironment has been shown to shape metabolic and cellular plasticity, increasing metastatic competence." (PMID 39595571, 2024). "The increased expression of PFKFB4 after senescence promotes cell stemness by enhancing glycolysis and pyruvate metabolism in breast cancer cells and reprograming the glucometabolic pathway in cancer cells." (PMID 38540708, 2024). "PFKFB4 enhances cancer stemness and contributes to chemoresistance to palbociclib in estrogen receptor–positive breast cancer." (PMID 37919747, 2023). "The overexpression of PFKFB4 was found in breast cancer, triple-negative breast cancer (TNBC), osteosarcoma, cervical cancer, clear-cell renal cell carcinoma, melanoma, HCC, glioblastoma, bladder cancer, gastric cancer, pancreatic cancer, and prostate cancer." (PMID 37919747, 2023). "PFKFB4 is also an emerging contributor in many cancer types including lung adenocarcinoma, breast cancer and gastric cancer." (PMID 37222403, 2023). "Our study illustrates the novel finding that PFKFB4 promotes angiogenesis in breast cancer via IL-6 instead of vascular endothelial growth factor (VEGF) which is a well-established mediator of angiogenesis in cancer." (PMID 34976184, 2022). "In this study, we found that PFKFB4 promotes angiogenesis via IL-6/STAT5A/P-STAT5 signaling in breast cancer." (PMID 34976184, 2022). "PFKFB4 ectopic expression in breast cancer cells elevates lactate levels in the conditioned medium which initiates NF-κB activation and nuclear translocation." (PMID 34976184, 2022). "In summary, we discovered that PFKFB4 plays a novel role in promoting angiogenesis in breast cancer." (PMID 34976184, 2022). "Elevated PFKFB4 transcription levels strongly correlated with shorter disease-free survival and overall breast cancer survival." (PMID 37193047, 2022). "We ectopically expressed PFKFB4 in human breast carcinoma MDA-MB-231 and T47D cells and established stable cell lines (i.e., MDA-MB-231/PFKFB4 and T47D/PFKFB4, respectively)." (PMID 34976184, 2022). "Recent studies have shown that metabolic enzyme PFKFB4 plays important roles in malignant breast tumors." (PMID 33593309, 2021). "Previous studies demonstrate that PFKFB4 is overexpressed in breast cancer, promotes breast cancer cell stemness and metastasis, and drives a protein signature that correlates with poor survival in patients." (PMID 34211613, 2021). "PFKFB4 has been reported to be involved in a variety of cancers including human bladder cancer, gastric cancer, colon cancer, breast cancer and other malignant tumors." (PMID 33593309, 2021).
breast cancer (continued). "In this study, we evaluated the prognostic power of PFKFB4 expression in 200 tumor samples from patients with stage I to III breast cancer." (PMID 31244553, 2019). "The inhibition of the expression of SRC-3 or PFKFB4 in animal models of breast cancer has been shown to lead to reduced tumor growth and metastasis." (PMID 31139559, 2019). "After stratification by molecular subtypes, PFKFB4 predicted poor DFS in luminal breast cancer (p = 0.018) and better OS was observed in TNBC patients with low PFKFB4 expression (p = 0.017)." (PMID 31244553, 2019). "Kaplan–Meier survival analysis revealed that breast cancer patients with high PFKFB4 expression demonstrated unfavorable disease-free survival (p = 0.008) and overall survival (p = 0.002)." (PMID 31244553, 2019). "To investigate the clinical significance of PFKFB4 in breast cancer, we conducted immunohistochemical staining for PFKFB4 expression in the tumor samples." (PMID 31244553, 2019). "To evaluate the clinical implications of PFKFB4 overexpression in breast cancer, we assessed the correlation between PFKFB4 status and DFS and OS using Kaplan–Meier survival analysis." (PMID 31244553, 2019). "We demonstrated that elevated PFKFB4 expression from immunohistochemistry analysis is associated with shorter DFS and OS in breast cancer." (PMID 31244553, 2019). "In breast cancer patients, PFKFB4 expression is increased along with enhanced levels of phosphorylated SRC-3 mainly in estrogen receptor-positive tumors and is associated with a poor survival." (PMID 31139559, 2019). "Our study revealed that almost half (49.0%, 98/200) of the breast cancer cases in our study had a score 3 (the highest) for PFKFB4 staining, which indicate a large population of breast cancer patients deposit the potential therapeutic target." (PMID 31244553, 2019). "In this study, we confirmed the prognostic value of PFKFB4 protein in breast cancer using immunochemistry, which can be easily performed in FFPE samples." (PMID 31244553, 2019). "Together, our findings establish the prognostic value of metabolic enzyme PFKFB4 in patients with operable breast cancer." (PMID 31244553, 2019). "Positive staining for PFKFB4 protein was observed mainly in the cytoplasm of breast cancer cells, and most of the intra- or extra-tumor stromal cells were negative for PFKFB4." (PMID 31244553, 2019). "Several studies identified PFKFB4 as a key molecule in multiple cancers, including breast cancer, prostate cancer and glioma." (PMID 31244553, 2019). "Moreover, they established the relationship between PFKFB4 (a rate-limiting enzyme involved in the cell glycolysis metabolic pathway, with dual functional activities of kinase and phosphatase) and breast cancer cell stemness." (PMID 38540708, 2024). "PFKFB4 increases proliferative action in breast cancer cells." (PMID 37919747, 2023). "CD44 ICD can also interact with CREB to bind to the gene promoter region of PFKFB4, a key enzyme of glycolysis, to regulate the transcription and expression of PFKFB4, thereby regulating breast cancer cell stemness and affecting breast cancer patient prognosis." (PMID 36964570, 2023). "Breast cancer cells were able to survive the harsh conditions of hypoxia by upregulating a glycolytic enzyme, 6-phosphofructo-2-kinase/fructose-2,6-biphosphatase-4 (PFKFB4), compared to the normoxic controls in vitro and in vivo." (PMID 37779896, 2023). "In this study, we investigated the role of PFKFB4 in angiogenesis of breast cancer." (PMID 34976184, 2022). "CD44ICD regulates PFKFB4-mediated glucose metabolism to facilitate breast cancer stemness." (PMID 36368999, 2022). "Moreover, the mRNA expression of PFKFB4 served as prognostic biomarker in solid tumors including breast cancer, bladder cancer and non-small cell lung cancer." (PMID 34593007, 2021). "In addition, one study indicated that PFKFB4 promotes breast cancer metastasis in a p38-dependent manner that initiates HAS2 transcription and expression." (PMID 33803236, 2021).
breast cancer (continued). "In recent years, PFKFB4, acting as a protein kinase, has been found to play a vital role in many cancers including glioblastoma, bladder cancer, gastric cancer and pancreatic cancer, breast cancer and so on." (PMID 33593309, 2021). "In addition, CD44ICD (CD44 molecule (Indian blood group)) leads to breast cancer stemness through the PFKFB4(6-phosphofructo-2-kinase/fructose-2,6-biphosphatase 4)-mediated metabolism of glucose." (PMID 34408553, 2021). "PFKFB4 is a regulatory enzyme that synthesizes a stimulator of glycolysis, and it is highly expressed in several types of cancer and correlates with poor survival in breast cancer patients." (PMID 33803236, 2021). "Furthermore, it was shown in breast cancer cells that PFKFB4 phosphorylated the oncogenic steroid receptor SRC-3, which increased its transcriptional activity and resultant pro-proliferative action." (PMID 33671514, 2021). "Similarly, increased transcription of PFKFB4 is observed in pancreatic cancer, gastric cancer, ovarian cancer, breast cancer, colon cancer and glioblastoma." (PMID 33671514, 2021). "Furthermore, in breast cancer, it was discovered that the enzyme PFKFB4 activates the transcriptional coactivator SRC-3 to drive the occurrence and development of tumors." (PMID 34211613, 2021). "Metabolic enzyme PFKFB4 promotes transcriptional co-activator SRC3 (nuclear receptor coactivator 3) for breast cancer carcinogenesis and is associated with poor prognosis of breast cancer." (PMID 34408553, 2021). "It has been reported that metabolic enzyme PFKFB4 could promote breast cancer progression by activating the oncogenic steroid receptor coactivator-3 (SRC-3)." (PMID 33593309, 2021). "Here we show the prognostic value of PFKFB4 expression in patients with operable breast cancer." (PMID 31244553, 2019). "Our results established that PFKFB4 is an independent prognostic factor in breast cancer." (PMID 31244553, 2019). "Our results indicated that elevated PFKFB4 is strongly associated with shorter disease-free survival (DFS) and overall survival (OS) and indicate that PFKFB4 could serve as a novel prognostic factor in breast cancer." (PMID 31244553, 2019). "Our study indicates the prognostic value of PFKFB4 protein in breast cancer." (PMID 31244553, 2019). "High expression of PFKFB4 was associated with reduced DFS and OS in breast cancer." (PMID 31244553, 2019). "Moreover, since PFKFB4 can regulate ER, we further investigated the survival relationship of PFKFB4 in breast cancer patients stratified by ER status." (PMID 31244553, 2019). "In several breast cancer cell lines, PFKFB4 expression increased upon exposure to hypoxia." (PMID 30234009, 2018). "The experimental outcomes also may potentially be affected by compensatory upregulation of other PFKFB isoforms such as PFKFB4 which likely explains the differences that we observed in the growth of the more gradual K-ras-driven lung tumor model relative to the Erbb2 mammary tumor model." (PMID 39001392, 2024). "Thus, PFKFB4 was established to be an independent prognostic factor in breast cancer." (PMID 31244553, 2019). "PFKFB4 exhibited substantial upregulation in bladder cancer (BLCA) and breast cancer (BRCA) with high statistical significance." (PMID 40739397, 2025). "The gene-gene interactions of deregulated glucose related genes in breast cancer, and it was found that deregulated glucose related genes show high interactions with PFKFB2, PFKFB4, FBP2, PCK2, ADH5 and other genes involved in glucose metabolism." (PMID 38173442, 2024). "In addition, PFKFB4 could phosphorylate SRC to promote the progression of breast cancer and LUAD." (PMID 37500615, 2023). "PFKFB4, a Warburg pathway enzyme, regulates transcriptional reprogramming by activating SRC-3 to drive breast cancer." (PMID 36625999, 2023). "Our previous findings showed that PFKFB4 promotes lactate production and secretion in ZR-75-1 and SKBR3 breast cancer cells." (PMID 34976184, 2022).
breast cancer (continued). "Blocking PFKFB4 and SRC-3 suppressed cellular growth, prevented metastasis, and reduced the concentration of nucleotides in breast cancer cells." (PMID 33671514, 2021). "PFKFB4 phosphorylated and activated transcriptional coactivator SRC-3 to promote aggressive breast cancers." (PMID 33593309, 2021). "CD44ICD promotes PFKFB4 transcription and expression via interacting with CREB and contributes to the glycolysis and stemness of breast cancer cells." (PMID 34093813, 2021). "The authors examined 80 samples from the Cancer Genome Atlas and demonstrated that breast cancer patients with high SRC3 and PFKFB4 mRNA expression have unfavorable prognosis." (PMID 31244553, 2019). "Further study is needed to determine the expression pattern of PFKFB4 and SRC-3 and the activated status of the PFKFB4-SRC-3 axis in breast cancer." (PMID 31244553, 2019). "PFKFB4 (an isoform of PFK2) phosphorylates and activates oncogenic SRC-3 to promote breast cancers through stimulating purine synthesis." (PMID 31259690, 2019). "Furthermore, a new function for PFKFB4 in the activation of steroid receptor coactivator 3 (SRC-3), a transcriptional coactivator, has recently been shown in breast cancer." (PMID 36115843, 2022). "PFKFB4 was reported to phosphorylate SRC-3 (NCOA3) at Ser857 in breast cancer with no other report on its potential substrate." (PMID 34593007, 2021). "PFKFB4 is reported to be a robust stimulator to nuclear receptor coactivator 3 (NCOA3) which drives glucose flux towards the PPP and up-regulates the activity of estrogen receptor to further promote aggressiveness of breast cancer." (PMID 34593007, 2021). "PFKFB4 and SRC-3 are drivers of the growth of basal-subtype breast cancer." (PMID 31244553, 2019). "First, this is a retrospective study, in which we tested the association between PFKFB4 expression with DFS and OS in breast cancer rather than true prediction." (PMID 31244553, 2019). "PFKFB4 was recently shown to act as a protein kinase phosphorylating the oncogenic steroid receptor coactivator-3 (SRC-3) and enhancing its transcriptional activity to drive breast cancer." (PMID 30234009, 2018). "Specifically, we found that PFKFB4 promotes angiogenesis via IL-6 (not via VEGF) in breast cancer." (PMID 34976184, 2022). "Moreover, the PFK-2 isoform PFKFB4 directly phosphorylates and activates steroid receptor co-activator-3 (SRC-3), and the PFKFB4–SRC-3 axis drives primary growth and metastasis of basal-subtype breast cancer cells in a mouse xenograft model." (PMID 34240146, 2021). "Furthermore, the prognostic value of the PFKFB4 protein in breast cancer has not been investigated." (PMID 31244553, 2019).